RN7SL400P (RNA, 7SL, cytoplasmic 400, pseudogene)
Gene: Miscellaneous RNA gene on chromosome 15 (21,102,843 to 21,103,138, reverse strand). Ensembl gene ENSG00000243059.
Homologues: Orthologues: chimpanzee Metazoa_SRP (99% identical), macaque Metazoa_SRP (93% identical). Paralogues in human: RN7SL584P (100% identical), RN7SL633P (97% identical), RN7SL1 (79% identical), RN7SL2 (79% identical), RN7SL3 (78% identical), RN7SL220P (77% identical), RN7SL679P (76% identical), RN7SL797P (76% identical), RN7SL868P (76% identical), RN7SL464P (76% identical), RN7SL127P (75% identical), RN7SL655P (75% identical), and 701 more.